IL1B (interleukin 1 beta)
Diseases named in the same sentence as IL1B in open-access papers (continued):
Sharing a sentence is not in itself a finding about the gene and the disease.
steatosis (continued). "Considering that macrophages‐derived proinflammatory cytokines (IL‐1β, IL‐6, and TNF‐α) may regulate hepatocyte steatosis and apoptosis, we constructed a coculture system to observe whether a crosstalk exists between these two cell types." (PMID 39279458, 2024). "Although Shh drove the pathogenesis of NASH including steatosis, inflammation, and fibrosis, it did not induce the expressions of Il-1β, Tnf-α, and Il6 in bone marrow-derived macrophages (BMDMs)." (PMID 38342927, 2024). "After 1 and 2 h after LT, levels of IL-1β increased in livers with and without steatosis when undergoing LT and BD, but hepatic IL-1β was more elevated in steatotic livers than those recorded in respective analogous groups with non-steatotic livers." (PMID 37593740, 2023). "Notably, NAFLD progression from simple steatosis to NASH, with substantial fibrosis, is mediated by inflammatory cytokines, including IL-1β, IL-6, and TNFα, overproduced by resident liver macrophages, i.e., the inflammatory-polarized M1-Kupffer cells." (PMID 37510108, 2023). "For instance, compared to Zeb1WT/ApoeKO mice, Zeb1∆M/ApoeKO mice had higher body weight, greater steatosis, higher WAT immune infiltration, higher serum levels of pro-inflammatory markers (IL1β, IL2, IL12, leptin, CCL2), higher cholesterol and LDL, and lower HDL and glucose tolerance." (PMID 38097578, 2023). "In hepatic grafts from DBDs in which steatosis was present, the same level of administration of NO (BD+NO+LT) did not have an effect and was unable to induce changes in either IL-10 or IL-1β with respect to the experimental group BD+LT, without any treatment." (PMID 37593740, 2023). "Steatosis induces the production of pro-inflammatory mediators like TNF-α, IL-6 and IL-1β." (PMID 37705071, 2023). "Herein, we show new endogenous signaling pathways in LT from DBDs, namely, IL-6/IL-1β in non-steatotic liver grafts and IL-10/L-1β in steatotic ones; these different mechanisms that depend on the presence of steatosis had not been reported to date." (PMID 37593740, 2023). "Inflammatory biomarkers IL-1β, IL-6, IL-8, IL-10, and TNFα were all significantly elevated in the NAFLD/NASH patients, with respect to control participants and patients with simple steatosis." (PMID 36589452, 2022). "In addition, HLF increased the activities of plasma SOD, CAT, and GSH-Px and decreased the levels of Casp 1, NLRP3, IL-1β, IL-18, and TNF-α, improving the degree of hepatocyte steatosis and inflammatory infiltration of rats." (PMID 36425260, 2022). "Although no changes in hepatic gluconeogenesis gene expression were observed between WT and Gkn1−/− mice, there were significantly decreased levels of IL1β and IL6 mRNA in Gkn1−/− suggesting that the resistance to steatosis was accompanied by reduced hepatic inflammation in Gkn1−/− mice." (PMID 33947892, 2021). "Based upon the reduced Nlrp3 and IL-1β mRNA expression in the livers of both the DIO and ob/ob clodronate-treated mice, we hypothesized that IL-1β might play a key role in steatosis development in hepatocytes." (PMID 25216251, 2014). "Decreased gastric mRNA expression of CPE (-1.88, p<0.04) and IL1B (-2.5, p<0.05) was identified in patients with advanced steatosis compared to patients with mild or no steatosis." (PMID 25289139, 2014). "Therefore, the inflammatory cytokines TNF-α, IL-1β, and IL-18 may combine with CXCL1 to synergistically induce liver injury and steatosis." (PMID 40606614, 2025). "Thus, we observed that inhibition of IL-1β action reduced injury both in the presence and in the absence of steatosis, which means that IL-1β is involved in hepatic damage induced by BD and LT, in both types of grafts." (PMID 37593740, 2023). "Since IL-1β inhibition has been shown to be equally effective in the presence or absence of steatosis, clinicians did not have to worry about knowing the degree of fatty infiltration that a liver graft that is going to undergo transplantation could have." (PMID 37593740, 2023).
steatosis (continued). "Indeed, steatosis progression to steatohepatitis and fibrosis originates from the uncontrolled increase of oxidative damage and inflammatory cascade and then is sustained by the activation of NLRP3 inflammasome which promotes Casp1-dependent IL-1β production." (PMID 33265944, 2020). "When mRNA expression levels were compared in samples of patients with advanced steatosis (Grade ≥ 3) to that with mild or no steatosis (Grade < 3), significant decreases in expression levels of mRNAs encoding CPE (−1.88, p < 0.04) and IL1B (−2.5, p < 0.05) genes were observed." (PMID 24716593, 2014). "The analysis of the mRNA levels showed a significant increase in both the deleterious [Chop/Grp78] ratio (54-fold increase), and inflammasome components (caspase-4, caspase-1 and IL-1β) in NASH patients (n=9) compared with patients without NAFLD (n=6) and with steatosis (n=15)." (PMID 26355342, 2015). "Unlike current PCLSs models, which show only steatosis, lipid deposition, and lipotoxicity, human PCLSs under GFIPO after 96 h exhibited markers of liver inflammation, including up-regulated inflammatory genes (TNFα, IL6, and IL1β) and cytokines (TNFα, IL6, IL8), detectable up to 96 h." (PMID 38474754, 2024).
prostate carcinoma (112 papers, 1998 to 2026). A carcinoma that arises from epithelial cells of the prostate gland. "Treatment of recurrent prostate cancer patients with 200 μmol/day of SFN-rich broccoli sprout extract for 20 weeks also caused a statistically significant decrease in plasma levels of IL-1β, IL-4, and IL-13." (PMID 41802185, 2026). "CNP and prostate carcinoma patients are associated with prolonged overproduction of inflammatory cytokines, including IL‐1β, IL‐6, and TNF‐α." (PMID 40552335, 2025). "More recently, tumor-derived IL-1β was implicated in cross-talk between prostate cancer cells and adipocytes, leading to reduced sensitivity to docetaxel via lipolysis-dependent mechanisms." (PMID 39858071, 2025). "Androgen deprivation therapy (ADT) in prostate cancer patients is often associated with increased production of pro-inflammatory cytokines (e.g., IL1β)." (PMID 33923931, 2021). "For example, a drug which targets and activates NLRP3 can suppress IL-1β and IL-18 while causing prostate cancer pyroptosis and then limiting the scale and scope of inflammation." (PMID 34869390, 2021). "High-score values for IL-1β or low-score values for interferon (IFN)β (both measured by immunohistochemistry (IHC)) were significantly associated with biochemical recurrence of prostate cancer." (PMID 32635472, 2020). "Our findings are supported by the possibility that genetic polymorphisms in the IL-1β gene, which are linked to a higher risk of aggressive prostate cancer, are the causes of the different expression patterns of IL-1β and its receptors in PCa compared to normal prostate tissue." (PMID 39554609, 2024). "Additionally, other cytokines such as TNF-α, IL-8, and IL-1β have also been found to be associated with the development and progression of prostate cancer." (PMID 38833027, 2024). "This association was mainly observed in serum after diagnosis and the result suggests that the relationship between IL-1β and prostate cancer risk detected in case-control studies may be biased by reverse causation." (PMID 36733309, 2023). "In a case-control study, individuals carrying the IL-1β (rs16944 and rs1143627) AG genotype were related with a lowered risk of prostate cancer as determined by real-time polymerase chain reaction of blood samples from 71 prostate cancer cases and 76 controls." (PMID 36733309, 2023). "For PCa, previous studies reported that IL-1β, IL-4, and IL-16 gene polymorphisms could affect the incidence of prostate cancer." (PMID 36034203, 2022). "IL-1β was associated with inflammation-induced invasion of prostate cancer cells." (PMID 34822550, 2021). "Increased expression of NLRP12 in prostate cancer suggest that NLRP12 may play an important role in activating NF-κB and IL-1β signaling, and its association with the pathogenesis and progression of prostate cancer." (PMID 28663562, 2017). "The role of IL-6 and IL-1β is implicated in bone metastasis of prostate cancer cells." (PMID 28663562, 2017). "Dysregulation of PI3K/Akt signaling and constitutively active NF-κB have been recently implicated in the upregulation of IL-1β in prostate cancer cells and could be plausibly involved—at least in part—in the production and secretion of this cytokine, as previously reported for these cells." (PMID 39858071, 2025). "In addition to IL-1β and IL-6, several other cytokines have been associated with prostate cancer." (PMID 30158439, 2018). "Pre-clinical studies have shown how this can promote tumor progression and should be clearing the way for clinically assessing the therapeutic value of inhibiting IL-1β signaling in prostate cancer." (PMID 39858071, 2025). "In prostate cancer, the inhibitory effects of pterostilbene on circulating levels of IL-6 and IL-1β were reported in prostate cancer xenografts and transgenic mouse models." (PMID 40077738, 2025).
prostate carcinoma (continued). "This section will present evidence that different tumors (prostate cancer is discussed separately below) secrete IL-1β to aid their spreading to and colonization of secondary target tissues." (PMID 39858071, 2025). "Our group was the first to establish a functional link between IL-1β expression and the bone metastatic potential of prostate cancer cells in pre-clinical models." (PMID 39858071, 2025). "We conclude by reviewing the therapeutics currently used for blocking IL-1β signaling and propose a rationale for their concomitant use with standard-of-care treatments to improve the clinical outcomes of advanced prostate cancer." (PMID 39858071, 2025). "Special emphasis is placed on the potential role that the standard-of-care treatment strategies for prostate cancer patients have in unleashing IL-1β expression and production at metastatic sites." (PMID 39858071, 2025). "In models of prostate cancer, lycopene treatment induces a decrease in the concentration of inflammatory mediators such as TNF-α, IL-1β, IL-6, IL-8, IL-10, and TGF-β associated with a reduction in tumor growth and an increase in survival." (PMID 40420174, 2025). "Another study used non-cancerous prostate cell line PNT2 treated with extracellular vesicles (EVs) isolated from advanced prostate cancer PC3 cells (PC3-EVs) as a model to assess caspase-1–mediated IL-1β maturation after 24 hours of EV treatment." (PMID 40718836, 2025). "Chronic inflammation in the tumor microenvironment can lead to increased cytokine production (e.g., IL-6, TNF-α, IL-1β), which promotes both prostate cancer progression and the survival/proliferation of abnormal plasma cell clones in MGUS." (PMID 41374992, 2025). "In contrast, in prostate cancer, IL‐1β can mediate the metastasis of prostate cancer by activating IL‐8 through the MAPK pathway." (PMID 38652105, 2024). "Analogous results were obtained in prostate cancer models, in which the overexpression of IL-1β increased bone metastasis." (PMID 38334625, 2024). "Human prostate cancer (PCa) cells secreting IL-1β can convert the bone stroma into a metastatic niche by upregulating genes such as S100A4 and COX-2, which are involved in the formation of cancer-associated fibroblasts (CAFs)." (PMID 38334625, 2024). "This has sparked significant interest among researchers in targeting key enzymes and signaling pathways involved in the inflammatory response—such as COX-2, NF-κB, IL-6, and IL-1β—as potential therapeutic strategies for prostate cancer." (PMID 39355131, 2024). "Recently, the inhibition of IL-1β was found to reduce the metastatic potential of murine prostate cancer cells while its overexpression was increased." (PMID 38248645, 2023). "A high IL-1β expression in prostate cancer predicts good treatment prognosis and better progression-free survival." (PMID 38248645, 2023). "Collectively, these data showed that IL‐1β promotes immunosuppression in prostate cancer by inducing the accumulation of MDSCs." (PMID 37092583, 2023). "Our study has shown that IL-1β enhances proliferation of prostate cancer cells at physiological concentrations." (PMID 37449203, 2023). "Androgen receptor signaling is active in tumor‐associated macrophages (TAMs) and inhibits the transcription of IL‐1β in prostate cancer." (PMID 37092583, 2023). "A previous study found that NLRP12 inflammasome induces inflammatory events during the development and progression of aggressive prostate cancer via regulating IL-1β and IL-18." (PMID 37658975, 2023). "And, when LNCaP prostate cancer cells are co-cultured with fibroblasts, the high expression of IL-1β is antiproliferative." (PMID 38248645, 2023). "RSPO3 down regulation is involved in prostate cancer invasiveness and interacts with the inflammatory mediator IL-1β." (PMID 37226243, 2023).
prostate carcinoma (continued). "As for immunology pathways, in a study of a rat model of prostate cancer bone metastases, electroacupuncture was found to inhibit pro-inflammatory cytokines, such as IL-1β, which attenuate nociceptive receptor sensitivity and inhibit pain transmission." (PMID 37255718, 2023). "The authors conclude that the cytokines IL-1α, IL-1β, IL-6, and IL-8 have a significant role in prostate cancer development." (PMID 37048115, 2023). "Of all possible combinations analyzed, the combination of IL1B-31 (rs1143627) G and IL1B-511 (rs16944) G prevented the development of prostate cancer." (PMID 36034203, 2022). "Prostate cancer is an inflammatory disease; however, we found that 4/11 (36.4%) inflammatory markers (IL-8, IL-1β, NSE, and IL-6 levels) were significantly lower in the PCa patients." (PMID 35664747, 2022). "This new evidence lends strong support to the utility of IL1β antagonism in prostate cancer, particularly for patients with an unmethylated IL1β promoter and/or gene." (PMID 36561929, 2022). "Screening of a panel of human epithelial cancer cell lines revealed that the highest DKK1 and IL1B mRNA expression coincided in PC3 prostate cancer cells." (PMID 36539532, 2022). "Prostate carcinoma cells engage bone marrow adipocytes in a functional cyclooxygenase-2 (COX-2)-dependent cross-talk that promotes IL-1β expression, leading to docetaxel resistance." (PMID 35530309, 2022). "We report the inverse association between the expression of androgen receptor (AR) and IL1β in a cohort of patients with metastatic castration-resistant prostate cancer." (PMID 36561929, 2022). "Taken together, simulated μg induced 3D growth of PC-3 cancer cells combined with a differential expression of the cytokines IL-1α, IL-1β, IL-6 and IL-8, supporting their involvement in growth and progression of prostate cancer cells." (PMID 35252204, 2022). "Previous studies, using whole-genome DNA methylation analysis and global transcription analysis with human prostate cancer cell lines, revealed that the IL1β locus is hypermethylated in DU-145 cells in comparison with LNCaP and PC3-ML cells." (PMID 36561929, 2022). "The current standard of care for patients with prostate cancer inhibits the AR-signaling axis in tumor cells and will consequently unleash IL1β production." (PMID 36561929, 2022). "Our study aimed to address these pressing issues and investigate the incidence and mechanistic foundation for how AR signaling regulates IL1β expression in prostate cancer." (PMID 36561929, 2022). "According to our findings, PC3, a prostate cancer cell line, released the highest amount of IL-1β, while A549, a lung adenocarcinoma cell line, secreted low level of IL-1β." (PMID 34577552, 2021). "NLRP12 has similar functions to TGF-β and can also promote the occurrence and development of prostate cancer by regulating caspase-1 and its downstream IL-1β and IL-18." (PMID 34869390, 2021). "It was established that IL-6 is elevated in tissues of BPH and prostate carcinomas in men74 and intratumoral IL-1β levels significantly correlate with biochemical recurrence in prostate cancer patients." (PMID 33772116, 2021). "Other inflammatory cytokines with demonstrated reduction after ADT in prostate cancer patients include IL-1β, IL-2, tumor necrosis factor (TNF)-α, and interferon (IFN)-γ." (PMID 34926085, 2021). "Increased CTH (Cystathionine Gamma-Lyase) expression in patients with advanced prostate cancer is associated with poor survival, and H2S produced by CTH promotes the progression and metastasis of prostate cancer through the IL-1β/NF-κB signaling pathway." (PMID 33718182, 2021). "IL‐1β‐expressing prostate cancer cells generated a higher load of bone metastasis than prostate cancer cells that do not express this cytokine." (PMID 32761606, 2021).